IRX3 (iroquois homeobox 3)
Diseases named in the same sentence as IRX3 in open-access papers (continued):
Sharing a sentence is not in itself a finding about the gene and the disease.
melanoma (2 papers, 2021 to 2023). A malignant, usually aggressive tumor composed of atypical, neoplastic melanocytes. "However, additional investigations are warranted to gain a comprehensive comprehension of the underlying mechanisms through which IRX3 influences melanoma development." (PMID 38077400, 2023). "Notably, investigations have revealed that heightened expression of IRX3 is strongly associated with diminished survival rates and heightened vulnerability to metastatic disease in individuals diagnosed with melanoma." (PMID 38077400, 2023). "IRX3 (Iroquois Homeobox 3) is a risk biomarker for melanoma patients." (PMID 34769455, 2021). "The results showed that silencing of IRX3 led to smaller colonies in both A375 and WM-115 cells, suggesting that IRX3 silencing inhibits melanoma cell proliferation." (PMID 38077400, 2023). "The suppressive impact of IRX3 gene silencing on melanoma cell behavior implies the potential utility of targeting IRX3 as a therapeutic strategy with promising prospects." (PMID 38077400, 2023). "Extensive research has elucidated that downregulating IRX3 expression significantly reduces the invasiveness and proliferation of melanoma cells." (PMID 38077400, 2023). "To investigate the role of IRX3 in melanoma, we performed a colony formation assay on A375 and WM-115 melanoma cells in the NC and si-IRX3 groups." (PMID 38077400, 2023). "To explore the effect of IRX3 on melanoma cell migration and invasion, we conducted scratch assay and transwell assay." (PMID 38077400, 2023). "The overexpression of IRX3 in melanoma indicates its plausible involvement in tumorigenesis and disease advancement." (PMID 38077400, 2023). "Inhibition of melanoma cell proliferation, invasion, and migration was observed upon silencing of IRX3, while simultaneously promoting apoptosis." (PMID 38077400, 2023). "To further validate the expression of IRX3 in melanoma, we selected 20 pairs of melanoma and corresponding normal tissues for qPCR verification." (PMID 38077400, 2023). "The identified signature establishes a link between the IRX3 gene and an adverse prognosis in melanoma." (PMID 38077400, 2023). "In the current study, we found that higher expressions of FGD1, CSNK1E, and IRX3 are correlated with shorter survival of melanoma patients." (PMID 34769455, 2021). "Nevertheless, our study pioneers the examination of IRX3’s distinctive function in melanoma." (PMID 38077400, 2023). "The potential therapeutic value of targeting IRX3 in melanoma treatment holds great promise." (PMID 38077400, 2023). "Moreover, our in vitro experiments revealed that the silencing of IRX3 in melanoma cells resulted in the suppression of cell proliferation, invasion, and migration while promoting apoptosis." (PMID 38077400, 2023). "The role of IRX3 in tumor management, particularly in melanoma, is of utmost significance." (PMID 38077400, 2023). "Therapeutic targeting of the IRX3 gene may benefit melanoma patients." (PMID 38077400, 2023). "By analyzing the TCGA genomics, we also found that the gene alteration rates in the melanoma TCGA dataset were 12% for DDX60, 5% for CSNK1E, 2.8% for FGD1, 2.1% for GBP4, 4% for IFIH1, 1% for DOK1, and 0.7% for IRX3, and these alterations were not significantly correlated with mRNA expression." (PMID 34769455, 2021).
Osteopenia (2 papers, 2021 to 2025). Osteopenia is a term to define bone density that is not normal but also not as low as osteoporosis. "A recent study showed that mice with global KO of either IRX3 or IRX5 exhibit osteopenia, a precursor state of osteoporosis, with impaired osteoblast differentiation and increased bone marrow adipogenesis." (PMID 40769964, 2025). "In mice, Irx3 and Irx5 compound deletion mutants die at mid-gestation due to cardiac defects and skeletal malformation, whereas conditional deletion of Irx3/5 using osteoblast-specific Osx-Cre in mice results in osteopenia in postnatal growth." (PMID 34064134, 2021).
acute kidney injury (1 paper, 2025). Sudden and sustained deterioration of the kidney function characterized by decreased glomerular filtration rate, increased serum creatinine or oliguria. "Further significantly upregulated transcripts related to inflammatory processes included ADAM19, PD-L1 (CD274), non-canonical NF-kB genes NFKB2 and RELB, furthermore IFITM1, JAML -linked with acute kidney injury - IRX3-linked with metabolic inflammation - and PRDM1-observed in gouty arthritis." (PMID 40281125, 2025).
acute leukemia (1 paper, 2018). A clonal (malignant) hematopoietic disorder with an acute onset, affecting the bone marrow and the peripheral blood. "Our studies demonstrate that tissue-inappropriate misexpression of IRX3 is both frequent and functional in human acute leukemias of multiple lineages." (PMID 29346763, 2018). "Our in vitro and in vivo studies demonstrate that misexpression of IRX3 contributes to the cardinal pathologic feature of acute leukemia, the differentiation block." (PMID 29346763, 2018). "report that the Iroquois homeodomain transcription factor gene IRX3 is frequently derepressed in human acute leukemias of multiple lineages and contributes to the differentiation block, which is the pathognomonic feature of the disease." (PMID 29346763, 2018). "In summary, we demonstrate that the Iroquois homeodomain transcription factor IRX3 is frequently misexpressed in human acute leukemia to contribute to the differentiation block that is the pathognomonic feature of the disease." (PMID 29346763, 2018). "Critically, the same transcriptional signature of IRX3-mediated repression of myelomonocytic differentiation was readily identified in human AML, confirming that IRX3 misexpression is both frequent and functional in human acute leukemia." (PMID 29346763, 2018). "Thus, tissue-inappropriate derepression of IRX3 contributes significantly to the block in differentiation, which is the pathognomonic feature of human acute leukemias." (PMID 29346763, 2018). "We now report a functional role for IRX3 in human acute leukemia." (PMID 29346763, 2018). "The molecular consequences of IRX3 misexpression in the acute leukemias remain unclear." (PMID 29346763, 2018). "Given this, and the observation that IRX3 is highly expressed in a subset of AML patients, we evaluated whether IRX3 has a functional role in acute leukemia." (PMID 29346763, 2018).
ampullary cancers (1 paper, 2016). "This 3-gene expression model suggests that the collective expression of IRX3, PYCR1, and TMPRSS3 reflects the additional biological importance of tumor invasion, intestinal differentiation, and cellular metabolism, in the prognosis of ampullary cancers." (PMID 27549176, 2016).
Arrhythmia (1 paper, 2016). Any cardiac rhythm other than the normal sinus rhythm. "In vitro experiments also showed that mutated forms of IRX3 led to reduced transcriptional regulation compared to wild-type IRX3, suggesting that these mutant IRX3 alleles associated with arrhythmia act as hypomorphic or loss-of-function mutations." (PMID 26786475, 2016).
Cachexia (1 paper, 2017). Severe weight loss, wasting of muscle, loss of appetite, and general debility related to a chronic disease. "When considering the possible molecular mechanism from FTO via IRX3 to OLIG2 resulting in greater lifelong motor neuron availability, this may have implications for muscle size-related disorders such as sarcopenia and cachexia." (PMID 28103813, 2017).
colorectal adenoma (1 paper, 2017). An adenoma that arises from the colon or rectum. "Analizing data of the transcriptional profiles of human colorectal adenoma samples showed IRX3 as one of the most up-regulated transcription factors compared to normal tissue." (PMID 27901484, 2017).
gastric cancer (1 paper, 2023). A primary or metastatic malignant neoplasm involving the stomach. "IRX3 was also identified as an IRTF, and its downregulated expression was found to be a key element involved in a transcription factor regulation network analysis in Epstein–Barr virus-associated gastric cancer (EBVaGC)." (PMID 36980893, 2023).
glioblastoma (1 paper, 2025). The most malignant astrocytic tumor (WHO grade IV). "Emerging evidence indicates that IRX3 plays critical roles in the development of some cancers, but the specific functions and molecular mechanisms of IRX3 in glioblastoma (GBM) remain unknown." (PMID 41436436, 2025).
Hamamy syndrome (1 paper, 2016). "Since the global loss of both Irx3 and Irx5 leads to cardiac phenotypes similar to those seen in Hamamy patients, we wanted to see if the decreased mineralization we found in Irx3flox/flox/Irx5−/−/Osx-Cre+ mice also reflected the clinical presentation of Hamamy syndrome patients." (PMID 27453922, 2016). "More detailed analysis of Hamamy syndrome patients cells using a human induced pluripotent stem cell model may help demonstrate the dynamics of IRX3 and IRX5 interactions in Hamamy patient cells." (PMID 27453922, 2016).
Hodgkins lymphoma (1 paper, 2021). A heterogeneous group of malignant lymphoid neoplasms of B-cell origin characterized histologically by the presence of Hodgkin and Reed-Sternberg (HRS) cells in the vast majority of cases. "Subsequent expression analysis of TALE homeobox genes in public datasets of Hodgkin lymphoma (HL) patients revealed overexpression of IRX3, IRX4, MEIS1, MEIS3, PBX1, PBX4 and TGIF1." (PMID 33539429, 2021).
hypospadias (1 paper, 2025). Hypospadias is the displacement of the urethral meatus on the ventrum of the penis. "It is reported that SNP loci located in other homologous gene box families (such as HOXA cluster, IRX3, IRX5, ZFHX3, etc.)also increase the risk of hypospadias, which may suggest the focus of the future research." (PMID 40547448, 2025).
idiopathic ventricular fibrillation (1 paper, 2017). "Two heterozygous IRX3 mutations have been linked to idiopathic ventricular fibrillation in humans, suggesting that nonsynonymous variant in IRX3 could be functional and lead to certain diseases." (PMID 28988979, 2017).
ischemia (1 paper, 2015). A hypoperfusion of the BLOOD through an organ or tissue caused by a PATHOLOGIC CONSTRICTION or obstruction of its BLOOD VESSELS, or an absence of BLOOD CIRCULATION. "Indeed, pharmacological approaches to regulate IRX3 expression and function during adult angiogenesis, in the context disease-induced ischemia, may provide exciting new therapeutic opportunities." (PMID 25512384, 2015).
ischemic heart disease (1 paper, 2023). "Prex1 and Irx3 are suggested as potential modifier genes of cardiac Cu content, while Ctsa, Mmp2, and Armcx1 may closely be related to ischemic heart disease." (PMID 36818345, 2023).
myeloid leukemia (1 paper, 2018). A clonal proliferation of myeloid cells and their precursors in the bone marrow, peripheral blood, and spleen. "qPCR analysis of genes associated with self-renewal in myeloid leukemia demonstrated significant upregulation of Myc and Myb in IRX3+ populations with significant clonogenic potential (P1 and P2)." (PMID 29346763, 2018).
osteoarthritis (1 paper, 2023). A noninflammatory degenerative joint disease occurring chiefly in older persons, characterized by degeneration of the articular cartilage, hypertrophy of bone at the margins and changes in the synovial membrane. "For example, we found that all measures of adiposity have a causal effect on higher expression of IRX3 in synovium or pancreatic islets and on lower expression of RTN2 in osteoarthritis cartilage." (PMID 37433298, 2023).
pheochromocytoma (1 paper, 2017). "Consistently, IRX3/Irx3 expression was induced during the browning process of WAT in humans (pheochromocytoma patients) and β3-adrenergic agonist-stimulated mice, supporting the physiological role of IRX3 in browning." (PMID 28988979, 2017). "We therefore further validated IRX3 expression in the beige adipocytes from pheochromocytoma patients." (PMID 28988979, 2017).
polycystic ovary syndrome (1 paper, 2024). A disorder that manifests as multiple cysts on the ovaries. "Ets1 has been implicated in the pathogenesis of polycystic ovary syndrome, while Irx3 has been reported to be essential for oocyte quality control through ECM production." (PMID 39441825, 2024).
prediabetes (1 paper, 2023). "In our study, we also identified an intergenic SNP (rs9929651) between IRX3 and CRNDE, as well as multiple SORCS2 SNPs, that showed significant associations with HDL-C levels in individuals with prediabetes." (PMID 38371897, 2023).
right bundle branch block (1 paper, 2020). "Mice with IRX3 knocked out exhibit abnormal cardiac electrophysiology, including extended QRS complex duration, extended conduction time between the atrioventricular bundle and the ventricles, and right bundle branch block (RBBB)." (PMID 32192102, 2020).
skin cutaneous melanoma (1 paper, 2023). "Higher expression of IRX1, IRX2, IRX3, IRX5, and IRX6 all display statistically significant unfavorable prognosis for skin cutaneous melanoma." (PMID 37084727, 2023).
tumor (13 papers, 2015 to 2025). "In MB, high expression of lnc-IRX3-80 seems to promote tumor growth and is associated with cisplatin resistance." (PMID 37835380, 2023). "Deletion of the wild-type allele of ETV6 in REH cells supported the tumor suppressor status of this gene and indicated a potential mechanism of escaping IRX3-mediated activation." (PMID 36233173, 2022). "IRX3 may be implicated in colorectal tumorigenesis by reducing tumor cell sensitivity to the Dpp/TGFβ pathway, granting tumor cells a growth advantage." (PMID 26980732, 2016). "Meanwhile, few genes were uniquely expressed in TERT altered tumours; amongst these were IRX3, SDK1 and TRIP13." (PMID 40097403, 2025). "Meanwhile, few genes were uniquely expressed in TERT-altered tumours but included IRX3, SDK1 and TRIP13." (PMID 38978571, 2024). "In fact, transcript levels of lncRNA lnc-IRX3-80 are significantly higher in cisplatin-treated tumor cells." (PMID 37835380, 2023). "We further investigated the effect of IRX3 on tumor cell apoptosis." (PMID 38077400, 2023). "In tumor tissues, a significant upregulation of IRX3 was observed." (PMID 38077400, 2023). "Iroquois homeobox 3 (IRX3) plays vital roles in embryonic development, it has recently been reported to participate in tumor progression." (PMID 30258285, 2018). "The increased expression of IRX3 and TMPRSS3 in the poor prognosis ampullary subset is consistent with the biological functions of these genes in promoting tumorigenesis and tumor invasion, respectively." (PMID 27549176, 2016). "The upregulation of other homeobox transcription factors was also observed by us in cases of infratentorial tumor, which was shown to be connected with Iroquois homeobox transcription factors (IRX1, IRX2, IRX3, IRX5) and the PAX3 gene." (PMID 26497896, 2015). "Specifically, the CDC42EP3-206 + TMEM138-211 + IRX3-202-based model achieved maximum predictive efficacy (Rs = 0.94, FDR = 1.8e-09), explaining more than 88% of the ROR variance observed across different tumor types." (PMID 34899357, 2021). "Some candidate markers, such as IRX3, PDX1 and SCN2A, have not been found to be associated with tumours." (PMID 32649035, 2020).
cancer (7 papers, 2016 to 2025). A tumor composed of atypical neoplastic, often pleomorphic cells that invade other tissues. "Numerous studies have substantiated a notable correlation between the presence, advancement, and outcome of malignant tumors and the expression of the IRX3 gene." (PMID 38077400, 2023). "Statistical analysis showed that only one gene (IRX3) maintained a significant (FDR < 0.05) and concordant association in at least one of the four cancer datasets (not shown), and none maintained the association in all four datasets." (PMID 27902768, 2016). "Other members of the Iroquois (IRO/IRX) family, IRX1, IRX3 and IRX5 have been found differentially methylated and/or expressed between supratentorial and infratentorial PAs, suggesting that these genes may have an important role in specific location cancer development." (PMID 29568396, 2018).
IRX3 also shares sentences with these, for which no sentence is quoted: B-cell precursor acute lymphoblastic leukemia (2 papers); breast carcinoma (2); fatty liver disease (2); infection (2); prostate carcinoma (2); aortic stenosis (1); asthma (1); atrial fibrillation (1); cardiovascular disease (1); diabetic nephropathy (1); esophageal squamous cell carcinoma (1); Genetic obesity (1); gouty arthritis (1); lipoma (1); lymphoma (1); malignant epithelial tumours (1); metabolic disorders (1); metastatic disease (1); osteoporosis (1); psoriasis (1); sarcopenia (1); Splenomegaly (1); Stillbirth (1); T-cell ALL (1); Ventricular arrhythmia (1).